SOX2 (SRY-box transcription factor 2)
Diseases named in the same sentence as SOX2 in open-access papers (continued):
Sharing a sentence is not in itself a finding about the gene and the disease.
lung squamous cell carcinoma (64 papers, 2010 to 2026). "SOX2 overexpression has been linked to favourable outcomes in lung squamous cell carcinomas, while nicotine has been shown to induce the expression of SOX2 in non-small cell lung adenocarcinoma cells." (PMID 39595659, 2024). "Sox2, Oct4, and Nanog also demonstrated a high diagnostic potential and a potential future use in targeted therapy for adenocarcinoma and squamous cell lung cancer." (PMID 37761837, 2023). "Previously, SOX2 overexpression was reported to be associated with favorable prognosis in squamous cell lung carcinoma, but was correlated with poor survival in adenocarcinoma." (PMID 26706028, 2015). "In fact, SOX2 amplification and its pathogenic role association with oncogenesis have been reported in human lung squamous cell carcinoma." (PMID 24404135, 2014). "However, amplification and overexpression of SOX2 are associated with more prolonged survival in squamous cell lung cancer." (PMID 39439549, 2024). "However, SOX2 overexpression and gene amplification associates with favorable outcome in lung squamous cell carcinomas (SCC) and dissimilar results have been reported in lung adenocarcinomas (ADC)." (PMID 23620753, 2013). "Using these scores, we investigate non–small cell lung cancer samples, highlighting that SOX2 amplification is the dominant copy number alteration in lung squamous cell carcinoma and the main distinction to lung adenocarcinoma." (PMID 40971591, 2025). "Here, the authors develop iPANDDA, a network-based computational pipeline that integrates multi-modal data to predict drug targets for SOX2-dependent lung squamous cell carcinoma, identifying and validating key targets like AKT and mTOR complexes." (PMID 41388088, 2025). "In contrast, several studies implicated that high‐expression levels of SOX2 were significantly associated with lower probability of metastasis and a better prognosis in HNSCC and lung squamous cell carcinoma." (PMID 39180200, 2025). "In patients with lung squamous cell carcinoma higher levels of SOX2 expression were as well related to younger age and smaller tumor size." (PMID 39180200, 2025). "Specifically, SRY-box transcription factor 2 (SOX2) is a key determinant of squamous cell fate and promotes squamous cell carcinoma of the lung." (PMID 38093367, 2023). "For instance, in esophageal and lung squamous cell cancer cell lines, SOX2 and p63 — another TF upregulated in differentiated EEC in EoE — were shown to jointly occupy multiple genomic loci." (PMID 37672481, 2023). "The immunohistochemistry experiments on lung squamous cell carcinoma show that the lung tissues SOX2, KRT 5, KRT14, EPCAM and PD-L1 have a significant expression." (PMID 36056339, 2022). "LSD1 inhibition repressed the expression of SOX2 in lung squamous cell carcinomas, resulting in the suppression of SOX2-mediated oncogenic potential." (PMID 34082769, 2021). "By contrast, in squamous cell lung carcinoma, SOX2 expression frequently coincides with amplifications at its chromosomal locus, so that SOX2 stains rather homogenously in tumor biopsies and has been described as a lineage-survival factor." (PMID 31477842, 2020). "By comparison, in lung squamous cell carcinomas, similar patterns of chromothripsis followed by SOX2 amplification are characterized by many amplified SNVs, suggesting a later event in the evolution of these cancers." (PMID 32025007, 2020). "In a recent study, it was found that PKCI phosphorylates Sox2 at T118 site and drives tumorigenecity and cancer stem-like features in human lung squamous cell carcinoma cells." (PMID 29401647, 2018). "As an example, high SOX2 expression in lung squamous cell carcinoma (SCC) is related to a favorable prognosis, while it is associated with poor outcome in lung adenocarcinoma." (PMID 29596469, 2018). "Recently, one study described a SOX2 post-translational modification (phosphorylation) in human lung squamous cell carcinoma cells." (PMID 28388544, 2017).
lung squamous cell carcinoma (continued). "Since the SOX2 amplification was identified in lung squamous cell carcinoma (lung SCC), SOX2 transcriptional downstream targets have been actively investigated; however, such targets are often cell line specific." (PMID 26846300, 2016). "A study of tracheobronchial basal cells reveals a mechanism by which lung squamous cell carcinoma is almost universally initiated by exploitation of a stem cell injury response involving SOX2 and PI3K." (PMID 27880766, 2016). "SOX2OT and SOX2 co-upregulation has been reported in lung tumor tissues, particularly in squamous cell lung carcinoma, which is related to 3q26.33 genomic amplification." (PMID 26136768, 2015). "Another study, however, correlated SOX2 expression with lower grade and with better outcome in squamous cell carcinoma of the lung, and a recent study found a relation between SOX2 expression and advanced disease, as well as worse overall survival in SCLC." (PMID 24940116, 2014). "Recent study by Hussenet and his colleagues reported that SOX2 is an oncogene activated by recurrent 3q26.3 amplifications in human lung squamous cell carcinomas." (PMID 24727659, 2014). "In fact, SOX2 is up-regulated in lung squamous cell carcinoma, and activates cellular migration and anchorage-independent growth." (PMID 24423398, 2013). "Similar properties have been shown in lung squamous cell carcinoma lines where in vitro studies suggest SOX2-mediated induction of cell proliferation and anchorage independent growth." (PMID 21276239, 2011). "The next question that we considered was the possible functional consequences over-expression of SOX2 on lung squamous cell carcinomas." (PMID 20126410, 2010). "We find that SOX2 is overexpressed in human lung squamous cell carcinomas compared with adenocarcinomas." (PMID 20548776, 2010). "Another study with 147 subjects showed a correlation of Sox2 with squamous cell lung cancer, with Sox2 being present in 79% of the samples, demonstrating its crucial role in the diagnostic approach to this pathology with a high incidence and mortality in the world today." (PMID 37761837, 2023). "PRKCI/SOX2 signaling promotes the Hedgehog pathway and sustains lung squamous cell cancer stemness." (PMID 33924966, 2021). "SOX2 has been shown to be highly expressed in approximately 90 % of pulmonary squamous cell carcinoma and to a lesser extent in adenocarcinoma and several studies have previously identified SOX2 gene amplifications in lung squamous cell carcinomas with reported frequencies from 20 % to 60 %." (PMID 26780934, 2016). "Furthermore, SOX2 was also shown to be expressed in gastric and prostate cancers and more recently, was identified as a lineage-survival oncogene in squamous cell carcinomas of the lung." (PMID 21276239, 2011). "Recently, amplification of SOX2 has been described in human squamous cell lung cancers." (PMID 20548776, 2010). "Moreover, our findings raise the possibility of the activation of SOX2-dependent stem cell-related pathways in squamous cell carcinomas of the lung." (PMID 20161759, 2010). "Similarly, SOX2 silencing inhibits cellular proliferation in lung squamous cell carcinoma cells." (PMID 27225481, 2016). "ATF/SOX2 is another ZF-ATF against SOX2, which has been tested in mouse models of lung squamous cell carcinoma." (PMID 38612911, 2024). "For example, most (> 90%) of LSCC (Lung Squamous Cell Carcinoma) tumors exhibit an increase in copy number at chromosome 3q26, resulting in the upregulation of the PRKCI, SOX2, and ECT2 oncogenes and LSCC tumorigenesis." (PMID 38504159, 2024). "TTF1, KRT7, SOX2, P63, and KRT5 are biomarkers for poor prognosis of lung adenocarcinoma and lung squamous cell carcinoma." (PMID 38248716, 2023).
lung squamous cell carcinoma (continued). "Studies have shown that the SOX2 in tracheobronchial cells overexpressed with CDKN2A and PTEN deletion combination results in lung squamous cell carcinoma production." (PMID 36056339, 2022). "SOX2 is a well-known oncogene that has already been shown SCNA in HNSCC and lung squamous cell carcinoma." (PMID 31703248, 2019). "PKCι can also phosphorylate the transcriptional regulator of stemness, SOX2, enhancing its binding to the promoter of Hedgehog acyltransferase (HHAT) to facilitate the Hh target genes expression in lung squamous cell carcinoma." (PMID 30214681, 2018). "Desmocollin-3 was the most specific marker for poorly differentiated squamous cell lung carcinoma (100%), followed by CK5/6 (98.3%), glypican-3 (94.8%), Sox2 (94.8%), S100A2 (81%), S100A7 (75.9%), thrombomodulin (72.4%), p63 (48.3%), and HMCK (36.8%)." (PMID 28510121, 2017). "Co-amplification of SOX2 and Protein Kinase CI (PRKCI) has been reported to be responsible for the CSC phenotype in lung squamous cell carcinoma." (PMID 27225481, 2016). "Two of the four TFs we identified in squamous cell lung cancer (LUSC), TP63 and SOX2, are oncogenes that are overexpressed in LUSC through genomic amplification." (PMID 25994056, 2015). "Recently, SOX2 and TP63 were shown to interact functionally and co-localize to a large number of genomic binding sites in squamous cell lung cancer." (PMID 25994056, 2015). "It has recently been shown that co-amplification of SOX2 and PRKCI contributes to the aggressive behavior of lung squamous cell carcinoma, by promoting a stem-like phenotype through activation of the Hedgehog signaling." (PMID 25300947, 2014). "False versus true 3q chromosomal amplification in squamous cell lung carcinoma are observed and its impact to trials involving anti-PI3K and -SOX2 targeted drugs is a direct consequence." (PMID 23236352, 2012). "A suspected driver of lung squamous cell cancer (SCC) is basal cells, as a primary characteristic of lung SCC is basal cell metaplasia and increased expression of canonical basal cell markers like KRT5, SRY-box 2 (SOX2), and tumor protein p63." (PMID 39337350, 2024). "For example, SRY-Box Transcription Factor 2 (SOX2)-Overlapping Transcript (SOX2-OT) has been frequently detected in lung squamous cell carcinomas (SCCs), rather than in lung adenocarcinomas (LUADs)." (PMID 34692550, 2021). "Co-downregulation, or rather co-upregulation of SOX2 and β-catenin is not a common sight in squamous cell lung carcinoma since they have contradicting regulating behavior in respect to their proximal and distal speciation functions." (PMID 31935827, 2020). "They showed, that increased SOX2 and FGFR1 gene copy number is a common event in squamous cell lung cancer patients and could demonstrate their improved overall survival." (PMID 29596469, 2018). "When analyzing only poorly differentiated tumors, HMCK was the most sensitive marker for squamous cell lung carcinoma (100%), followed by p63 (97.8%), CK5/6 (87.0%), Sox2 (71.7%), thrombomodulin (58.7%), desmocollin-3 (52.2%), S100A2 (50%), glypican-3 (45.7%), and S100A7 (45.7%)." (PMID 28510121, 2017). "This study delineates a comprehensive landscape of 3447 lung squamous cell carcinoma (LUSC)‐specific oncogenic enhancers (SOEs), unveiling their pivotal role in driving tumor pathogenesis through enrichment of key transcription factors, including SOX2, p63, KLF5, and GRHL2." (PMID 40899632, 2025). "Therefore, we selected SOX2, KRT5 and KRT14 stemness gene proteins, PD-L1 immune related proteins, vimentin protein, and EpCAM protein, all of which influence epithelial carcinogenesis, to explore whether the mechanism at the cell level corresponds to lung squamous cell carcinoma pathogenesis." (PMID 36056339, 2022). "In lung squamous cell carcinoma, a good correlation between NANOG and SOX2 expression was observed; however, there was no clear correlation with survival outcome." (PMID 32635524, 2020).
non-small cell lung carcinoma (64 papers, 2010 to 2025). A group of at least three distinct histological types of lung cancer, including non-small cell squamous cell carcinoma, adenocarcinoma, and large cell carcinoma. "Previously, it has been shown that increased HOTAIR expression promoted tumor sphere formation in non-small cell lung cancer cells via upregulation of the stem cell-associated markers, including Sox2, Nanog, Oct3/4, c-Myc, β-catenin and Klf4." (PMID 29228709, 2017). "Interestingly, SOX2-induced expression of CXCL5 was previously linked to neutrophil recruitment in non-small-cell lung cancer." (PMID 38225383, 2024). "CircVMP1 targets the miR-524-5p-METTL3/SOX2 axis to promote cisplatin resistance in tumor cells, transmitting malignant features and cisplatin resistance to cisplatin-sensitive non-small cell lung cancer (NSCLC)." (PMID 39135913, 2024). "Overexpression of OCT-3/4, SOX2 and c-MYC in patients with non-small-cell lung cancer (NSCLC) is associated with a decrease in cellular differentiation, an increase in metastases and poor prognosis." (PMID 35081981, 2022). "Herein, we investigated the role of SOX2 and its regulatory signaling in cisplatin-treated non-small-cell lung cancer (NSCLC)." (PMID 35059870, 2022). "Autophagy inhibition enhanced the sensitivity of non-small cell lung cancer cells to osimertinib by decreasing the expression of SRY-box transcription factor 2 (SOX2), a marker of stemness." (PMID 35682560, 2022). "What is more, although near univocally described as an oncogene and driver of transformation, in gastric and non-small lung cell carcinoma SOX2 expression was in fact reported as a favorable molecular prognostic factor." (PMID 31477842, 2020). "Chelerythrine chloride (Chelerythrine) can downregulate β-catenin and inhibit CSC invasion, spheroid-forming ability, and the expression of the stem marker SOX2 in non-small cell lung carcinoma (NSCLC)." (PMID 32456660, 2020). "This study intends to investigate the expression and significance of Sox2 and Sox2 autoantibodies (Sox2-Ab) in tissue and serum of patients with non-small cell lung cancer (NSCLC)." (PMID 24229625, 2013). "The aim of this study was to detect the expression of Sox2 and Oct4 and analyze their clinical significance in human non-small-cell lung cancer (NSCLC)." (PMID 22837720, 2012). "The Sox2 signaling pathway was essential in CSCs development and that its deregulation effectively suppressed growth and metastasis of non-small cell lung carcinoma cells." (PMID 23554769, 2012). "Given the possibility that a proportion of human non-small cell lung cancers arise from SOX2 upregulation, this and future mouse models will be useful in testing existing and new therapeutics for this group of patients." (PMID 20548776, 2010). "A recent study has demonstrated that a SOX2+/p63- immunohistochemical profile correlates with high-grade histology across non-small cell lung cancer subtypes." (PMID 20548776, 2010). "For example, studies have demonstrated that circRNA exosomal membrane protein 1 of EVs in patient serum samples can serve as a novel biomarker for non-small cell lung cancer, and it promotes non-small cell lung cancer proliferation by regulating the miR-524-5p-METTL3/SOX2 axis." (PMID 40696664, 2025). "Importantly, LBL21 exhibited the ability to abrogate stem cell-like cancer side population (SP) cells in non-small cell lung cancer A549 cells associated with a downregulation of stem cell markers including OCT4, ABCG2, SOX2 and CD133." (PMID 28640251, 2017). "In addition, a recent meta-analysis reported that SOX2 expression presents a positive prognosis in non-small cell lung cancer." (PMID 26706028, 2015). "Moreover, another study performed FISH analysis in 447 resected non-small cell lung cancer (NSCLC) tissue samples and SOX2 amplification was associated with increased gene copy number of FGFR1 and PI3KCA genes." (PMID 25114775, 2014).
non-small cell lung carcinoma (continued). "Most importantly, we could demonstrate that the downregulated expression of SOX2 in SP achieved by siRNA knockdown did markedly decrease tumour growth and metastasis of D121 non-small cell lung cancer cells." (PMID 21468047, 2011). "In contrast, P38γ and P38δ activation may suppress CSCs development in non-small-cell lung cancer (NSCLC) through promotion of the ubiquitin-mediated degradation of SOX2, OCT4, NANOG, KLF4 and MYC transcription factors that normally contribute to the acquisition of cancer stem cell characteristics." (PMID 35409206, 2022). "Radiation-resistant non-small cell lung cancer (NSCLC) cell lines exhibit marked upregulation of CSC markers like SOX2, CD133, and ALDH, with SOX2 critically enhancing DNA repair mechanisms and radioresistance." (PMID 40693266, 2025). "In this context, our study aimed to evaluate the diagnostic performance of a panel of three genetic and epigenetic markers; HOXA9 gene promoter methylation, SOX2 and HV2 genes copy number variation in circulating cell free DNA in non-small cell lung cancer." (PMID 37038139, 2023). "For instance, GLI1-mediated regulation of SOX2 enhances CSC self-renewal and confers resistance to EGFR inhibitors in non-small cell lung cancer." (PMID 33958721, 2021). "In non-small cell lung cancers, YAP1 transcriptionally induces SOX2 through a physical interaction with OCT4." (PMID 34199594, 2021). "Besides, chelerythrine was identified to down-regulate the level of β-catenin and inhibited CSC invasion, spheroid formation and the expression of the stem marker SOX2 in non-small cell lung carcinoma (NSCLC)." (PMID 33276800, 2020). "Because the phosphorylation of HSP27 facilitates the ubiquitination and proteasomal breakdown of proteins that drive stemness (including NANOG, OCT4, c-Myc, SOX2, and KLF4) in non-small-cell lung cancer (NSCLC) cells, the inactivation of p38 promotes the expression of CSC characteristics." (PMID 41369386, 2025). "In our previous investigation, we identified 15 SOX2 related genes (4 negatively-correlated and 11 positively-correlated with SOX2) in lung SCC cells using RNA-seq data from 178 lung SCC specimens and another RNA-seq dataset from 105 non-small cell lung cancer cell lines." (PMID 29262545, 2017). "ATF4 transcriptionally activates serine biosynthetic genes in response to serine starvation in non-small cell lung cancer, and additionally, it has been shown to play a crucial role in the regulation of PSAT1 after OSN (Oct4, Sox2, and Nanog) was expressed in mouse embryonic stem cells." (PMID 29216929, 2017).